CD4 (CD4 molecule)
Diseases named in the same sentence as CD4 in open-access papers (continued):
Sharing a sentence is not in itself a finding about the gene and the disease.
infection (continued). "Very limited data have suggested that VNPs may share features of disease progression with progressors as well as harbor specific pathogenic signatures such as preservation of CD4+ stem cell central (TSCM) memory and preferential resistance to infection of CD4+ TSCM and CD4+ TCM subsets." (PMID 32194543, 2020). "Although the frequency of IFNγ-producing CD4+ T cells was significantly reduced in IL-6−/− mice 21 days after Mtb infection, comparable amounts of IFNγ-secreting CD4+ T cells could be detected during the following course of infection." (PMID 33375150, 2020). "Complex interplay of diverse CD4+ T cells that act synergistically to establish a well-orchestrated immune response is indispensable for host defence against Mtb infection, as a defective T-cell response leads to persistent infection and failure of resolution of TB." (PMID 32862519, 2020). "Thus a replication-competent and IFN antagonism-negative PRRSV vaccine will improve the host anti-viral immune response including the innate immunity, CD4+ T cells, CTLs, and B cells, and provide effective protection not only from homologous infection but also from heterologous infection." (PMID 31952177, 2020). "A better understanding of the mechanisms mediating the differentiation of CD4+ tissue-resident memory T cells will allow us to harness the protective capacity of this memory population and modulate their activity in the context of infection or inflammatory diseases." (PMID 32983171, 2020). "Specifically, IFN-γ−/− NR1 T cells (and endogenous CD4+ T cells that are likely antigen specific) become activated through the activity of C. trachomatis antigen and travel to the genital tract, where they are unable to clear infection because of their inability to produce IFN-γ." (PMID 32184237, 2020). "The role of macrophages is therefore somewhat unclear, although they are likely to play an important role as antigen presenting cells to CD4+ T cells in primary infection and might also act as effector cells, potentially destroying parasites through the production of reactive oxygen species." (PMID 32175341, 2020). "Furthermore, HIV productively replicated in humanized NOG-EXL mice, and infection induced a decrease in the percentage of CD4+ T cells, inversion of the CD4:CD8 ratio, and changes in cell populations, such as monocytes and dendritic cells, that recapitulated the pathology found in human infection." (PMID 33291453, 2020). "Although the mechanism for HIV entry into these CD4-negative cells in vivo remains elusive, studies have suggested it may rely on cell-associated infection (54, 59, 61, –, 63)." (PMID 32999017, 2020). "During the chronic phase on day 49 post-infection (‘chronic SIV’), CD4+ T cells remained at low levels in five animals or were restored to some extent in one animal which presented with lowest mucosal SIV DNA levels during both infection phases analyzed (animal #2)." (PMID 32616803, 2020). "Additionally, it is unknown whether viruses change their preference for different memory CD4+ T cell subsets from early to chronic disease stages during untreated infection." (PMID 32762760, 2020). "Thus, spontaneous viral clearance of HCV infection is characterized by vigorous and sustained specific CD4+ and CD8+ T cell responses during the acute phase of infection, while in contrast chronic infection is correlated with late, transient, weak, or narrowly focused CD4+ and CD8+ T cell responses." (PMID 32258171, 2020). "In the first set of experiments, clonal stocks of three NHP SIV strains SIVcpz LB715, MB897 and EK505 belonging to groups M and N; respectively, were inoculated into hu-HSC mice to determine whether they can establish infection in the human surrogate host and affect CD4+ T cell levels." (PMID 32849468, 2020).
infection (continued). "Consistent with the hypothesis, cellular analysis revealed that resistant Tac mice experience a significant increase in antigen-experienced CD4 T cells, Tfh cells, plasmablasts, and GC B cells at later stages of the infection." (PMID 33326773, 2020). "Also, preservation of CD4+ T cell counts over extended periods of infection in the face of ongoing viral replication presents an opportunity to evaluate T cell homeostasis and perturbations in T cell dynamics within these individuals compared to those with typical progression." (PMID 32194543, 2020). "As CXCR3 is a known target of T-bet, and is important for CD4+ T cell trafficking to sites of inflammation, this provides insight into a potential mechanism behind the reduced frequency and numbers of T cells found at, and adjacent to, the site of infection we found in our studies." (PMID 33373420, 2020). "Overall, our results suggest that an approach using the CD27MFI ratio on ESAT-6/CFP-10-specific total cytokine+ CD4+ T-cells could be used to discriminate between disease and infection in HIV-uninfected individuals and monitor treatment response during active TB, regardless of HIV status." (PMID 32131556, 2020). "By analysing cytokines associated with the major CD4+ve Thelper (Th) cell subsets (Interferon-gamma (IFN-γ)/Th1; Interleukin (IL)-4/Th2; IL-17A/Th17; IL-10/Tregulatory), we show that there is selective activation of PBMC producing IFN-γ and/or IL-10 during the latent phase following infection." (PMID 32487248, 2020). "CD4 T helper subsets mediate effective adaptive immune responses particularly when innate immune responses fail to eliminate pathogens; CD4 T cell responses also generate memory, which can quickly respond to the second infection of the same or similar pathogens." (PMID 33126494, 2020). "In conclusion, we have identified a novel alpha-toxin-dependent immunomodulatory strategy of S. aureus, which can directly act on CD4+ T cells and might be exploited for the development of novel immune-based therapeutic approaches to treat infections with antibiotic-resistant S. aureus strains." (PMID 32849537, 2020). "However, the HSV-2 encephalitis case differed in the background CD4+ T-cell count (130 cells per μL), a low level suggesting that this unusual infection might be classified as ‘opportunistic’." (PMID 32697807, 2020). "Furthermore, the percentage of infected cells that express antigen is very low initially and therefore the true ratio of effectors to antigen expressing CD4+ T cells at the start of the assay is very high and changes over time as both infection and expansion of HIV-specific CD8+ T proceeds." (PMID 32266164, 2020). "In contrast, multiple other studies have not found an association between CD4+ T-cell count and infection following surgery, with a wide range of preoperative CD4+ T-cell count values in patients with and without subsequent postoperative infection." (PMID 32787972, 2020). "For executing their effector functions, naïve CD4 T cells first need to be activated when receiving pathogen signals delivered by antigen-presenting cells (APCs), such as dendritic cells (DCs), and then differentiate into distinct T effector (Teff) populations based on the nature of infections." (PMID 33126494, 2020). "Similarly, it was tempting to associate the early IL-6 signaling in the liver with the parasite clearance and the subsequent elicitation and expansion of CD4 and CD8+ cells under the control of IL-6 shown to protect against infections caused by several pathogens." (PMID 33329563, 2020). "However, double infection had a limited impact on the decline in CD4+ T-cell counts than single infection (P > 0.05), which is consistent with the results of the study conducted on female sex workers in Kenya, but contradict findings obtained from the cohort of men with primary HIV infection." (PMID 32038599, 2020).
infection (continued). "Elevated Salmonella-specific CD4+ T cells in thymectomized mice are most likely a response to increased antigenic load from increased bacterial burdens, creating a feedback loop that then leads to greater expansion of Salmonella-specific CD4+ T cells throughout persistent time points of infection." (PMID 32722409, 2020). "Therefore, differentiation of CD4+ T cells to both these subsets by 4X-SA-GP immunization may help ensure that an effective T cell-mediated downstream response will occur upon infection." (PMID 32817694, 2020). "Additionally, CXCR3 was down regulated and CCR4 up regulated in memory CD4+ Treg exposed to ANDV-GP VLPs, this suggest that ANDV-GP could specifically act over CXCR3 in CD4+ Treg cells potentially altering their ability to migrate to the site of infection." (PMID 32984065, 2020). "Recent evidence suggest that CD4+TRM may influence local immune responses at the site of infection." (PMID 32098623, 2020). "Moreover, miR-126-3p is positively correlated with the subsets of CD4+ cells, but negatively correlated with infection time, suggesting that this miRNA may affect the progression of HIV and ART failure." (PMID 32319513, 2020). "HIV transmission to CD4+ T cells even after tenofovir and raltegravir treatment implies that most transfer occurs as a result of productive infection of CECs but that some (∼10%) transfer is not infection dependent, suggesting two separate mechanisms of trans-infection." (PMID 31772057, 2019). "Interestingly, we found trans-infection of CD4+ T cells by lysed CECs, indicating that CECs may serve as HIV carriers or reservoirs in HIV-infected individuals." (PMID 31772057, 2019). "However, in the context of HIV infection, establishment of these clusters of CD4+ TRM may also provide increased number of HIV-1 targets for the nascent infection, which can ultimately contribute to a larger reservoir after treatment." (PMID 31628331, 2019). "Moreover, using Il21-mCherry reporter transgenic (TG) mice, we found that lung CD4+ T cells had low basal mCherry expression, but the percentage and total number of Il21-mCherry expressing cells increased after infection with MRSA." (PMID 30969166, 2019). "Thus, myeloid DCs could mediate HIV-1 trans infection during their normal interaction with and signaling of immune responses in CD4+ follicular helper T cells (Tfh)." (PMID 31304185, 2019). "In addition, CD4+T cell count negatively correlated with infection-related indicators." (PMID 30994732, 2019). "It was reported that infection of S. mannii could promote the apoptosis of CD4+ T cells." (PMID 31572373, 2019). "Collectively, the results of the experiments with LysMCre+Ifnar1fl/fl and Ifnar1−/− mice infected via the IVag route indicate that CD4+ T cells are required to mount an efficient Ab response, to control the local viral burden, and to reduce clinical signs and mortality following IVag infection." (PMID 30677097, 2019). "Although confirmation in further studies will be required, these findings indicate that functional profiling of mycobacteria-specific CD4+ T cells could potentially be exploited for novel immune-based TB assays that enable the distinction between infection states based on a blood sample alone." (PMID 31024518, 2019). "Although intestinal CD4+ T cell depletion was significant in both groups, the percentage of CD4+ T cells expressing the proliferation marker Ki67 within the surviving CD4+ T cell population was significantly reduced in THC/SIV rhesus macaques until 180 days post infection." (PMID 31114576, 2019). "Interestingly, the A1 caliber decreased with increasing duration of infection, current CD4+ T-cell levels, and CVD risk in HIV+ subjects, but not in the HIV- controls (when relevant)." (PMID 31297086, 2019).
infection (continued). "➢ Activation of a CD4 T cell response, early production of Th1-IgG subtype IgG2b and local pro-inflammatory cytokine profile in infected animals.➢ An early Th1 and Th17 and reduced Tregimmune response is ineffective to prevent infection and leads to chronicity." (PMID 31396229, 2019). "Interestingly, when we performed a Spearman ranked correlation analysis, we found only a poor correlation between the frequency of Env-specific CD4+ T cells determined one week before FV challenge infection and the viral load in spleens 3 weeks after FV challenge infection (r = 0.1076; P = 0.5931)." (PMID 31568492, 2019). "Moreover, CVCC541 could elicit adaptive immune responses of host 11 days after infection upon examination of the proliferation and activation of CD4+ T cells." (PMID 30898022, 2019). "Next, we investigated whether there was any difference of the TIGIT/PD-1 co-expression of HCV–specific MHC class II tetramer+ CD4+ T cells during acute HCV infection between patients who progressed to chronic versus patients who spontaneously resolved the infection." (PMID 31337800, 2019). "Variability in cytokine expression of CD4+ T cells suggests that the initial classification of CD4+ T cells into subsets based on cytokine production and transcription factor expression will likely need to be revisited in the context of chronic antigen stimulation in infections." (PMID 31379821, 2019). "Furthermore, the same study that showed that macrophages can become infected via phagocytosis of CD4 T cells in an in vitro setting also demonstrated that the presence of ART prevents this infection from occurring and leads to degradation of viral DNA within 72 h." (PMID 31431552, 2019). "However, the effectiveness of moderately intensive chemotherapy or HSCT on the HIV reservoir had been minimal due to reinfusion of infected CD4+ T cells contaminating autografts, new infection of donor-derived CD4+ T cells, and chemotherapy-resistant infected cells." (PMID 31636630, 2019). "Furthermore, participants were categorized into two groups, according to CD4 < 500 and CD4 ≥ 500; [(i) sampling point: CD4-high, n = 16, CD4-low, n = 36; (ii) set-point: CD4-high, n = 16, CD4-low, n = 19; (iii) 1-year-infection point: CD4-high, n = 10, CD4-low, n = 22)]." (PMID 31836011, 2019). "At 4 weeks after implantation, increased numbers of total cells, CD3+ T cells, CD3+CD4+ helper T cells, F4/80 macrophages, M1 macrophages, and neutrophils were present in the infection-only group compared to infections treated with lysostaphin-delivering hydrogels and both sterile control groups." (PMID 31114804, 2019). "This, together with the dearth of memory CD4 T cells specific for epitopes within the more conserved internal virion proteins, could contribute to the increased morbidity seen in young children upon infection with a seasonal influenza virus." (PMID 30692574, 2019). "Thus, we speculated that these two receptors might come into play together to confer an accelerated rate of HIV trans-infection of CD4+ T cells." (PMID 31772057, 2019). "CD11chi Axl+ DCs have a cDC-like gene signature, which suggests they may play a similar role to other myeloid DCs in infection, namely efficiently transferring virus to CD4+ T cells and disseminating infection to other physical compartments such as the lymph nodes." (PMID 31156637, 2019). "Similarly, specific inhibition of HDAC6 by tubacin increased infection of CD4 + T cells by HIV-1." (PMID 31744547, 2019). "Therefore, the macrophages might contribute significantly to the reservoir by sustaining productive infection and facilitating new infection of CD4+ T cells." (PMID 30889861, 2019). "In addition to a cytolytic role in controlling infection, direct interactions with infected B cells and CD4 Tfh cells may also facilitate CD8 T helper-like functions in the follicle." (PMID 31275308, 2019).
infection (continued). "The discovery of CD4+ T cell subsets with polarised expression of specific cytokines has transformed our understanding of what constitutes a protective response and explains the diverse outcome on infection with the same pathogen in mice of different haplotype." (PMID 31365119, 2019). "In the SIVmac251 model, peripheral memory CD4 T cells expressing high levels of α4β7 were shown to be preferentially infected during the very early phase of infection and to be preferentially depleted from gut tissues as early as the first 2 weeks following infection in humans." (PMID 30811499, 2019). "Indeed, on performing intracellular flow cytometry we identified CD4+ cells as the source of the IL-17 produced during this infection, with additional gating showing significant increases in IL-17 seen within the CD4+CD3+ T-cell gated population during infection." (PMID 30998782, 2019). "However, dendritic cells retain viral particles at their surface that can remain infectious for several months and may contribute to the new infection of CD4+ T cells." (PMID 30889861, 2019). "We thus reasoned that IL-2 signals may have a greater impact on immune responses against heterosubtypic IAV infection than during primary responses against IAV where IL-2-producing CD4 T cells only reach the lung in significant numbers at 6 or 7 days post-infection." (PMID 31412088, 2019). "However, HIV-1 also exploits DCs as a means of transportation from the site of infection to the lymph nodes, where the high density of CD4+ T cells and direct cell-to-cell contact through immune synapses ease the spread of the virus and fast infection of a high number of cells." (PMID 31708924, 2019). "In addition to the influence of genetic factors like the IL-28 polymorphism that strongly determines the course of natural infection, it is thought that HCV-specific CD4+ T cell dysfunction followed by CD8+ T cell exhaustion and viral escape is the main reason for this loss of viral control." (PMID 31337800, 2019). "Infections in the absence of virion associated Vpr were characterized by low proviral transcription despite similar levels of integration, and reduced infection of CD4+ T cells in co-cultures." (PMID 31396206, 2019). "Upon specific infections, atrophy of the thymus is highly frequent in patients and is usually characterized by a block in thymocyte maturation (from DN to DP thymocytes), ultimately leading to a progressive and massive reduction of DP and SP (CD4+, CD8−) thymocytes." (PMID 31505755, 2019). "Moreover, this blocking effect was further confirmed using a wild type R5-tropic HIV-1NFN−SX to pulse mock treated or IFNα-treated CD3−HLA-DR+ cervical DCs, which were sorted and co-cultured with a reporter CD4+ cell line to measure viral transfer via trans-infection." (PMID 31114569, 2019). "This capacity to infect coreceptor+ cells without CD4 will obviously help variants to infect macrophages that express only low amounts of CD4 and could explain infection of astrocytes, which is sometimes detected in late-stage neurological disease." (PMID 30415390, 2019). "Hence, taken together, the increase in cell death observed following culture of CD4+ T cells in the presence of EBOV may at least in part be due to ER-stress following abortive infection." (PMID 31648236, 2019). "In C57BL/6J mice, the ratio of Th1/Th2 and Th17/Treg in the viral control group was significantly higher than that in the mock-treated controls, indicating that the infection with the influenza A virus FM1 strain could promote the differentiation of CD4+ T cells into Th1 and Th17 cells." (PMID 31757053, 2019). "Since we previously reported that CD4+ T cells play a limited role in protecting pregnant mice against primary infection via the RO route, our results here highlight the importance of exploring whether CD4+ T cells are protective when infection occurs intravaginally during pregnancy." (PMID 30677097, 2019).